CD38 (CD38 molecule)
Diseases named in the same sentence as CD38 in open-access papers (continued):
Sharing a sentence is not in itself a finding about the gene and the disease.
tumor (continued). "Moreover, isatuximab (SAR650984) is identified as another anti-CD38 mAb with potential anti-tumor cytotoxicity against MM." (PMID 33781320, 2021). "In addition, CD38 targeting moAbs have been shown to modulate the immunosuppressive tumor microenvironment by elimination of myeloid-derived suppressor cells, regulatory B cells and regulatory T cells." (PMID 34638393, 2021). "We aimed to develop mouse CD38-specific nanobodies and hcAbs, to assess their binding epitopes, and to evaluate their capacity to induce cytotoxicity against tumor cells expressing CD38 in vitro as a basis for future in vivo studies of syngeneic MM models in immunocompetent mice." (PMID 34539634, 2021). "Moreover, CD3 × CD38 BiTE antibody, engineered to direct T cells to CD38 on tumor cells, was also developed." (PMID 34072645, 2021). "To verify our hypothesis, we analyzed the expression of PD-1 and CD101 in tumor-infiltrating CD38+ CD8+ T cells and CD38− CD8+ T cells by flow cytometry." (PMID 33934206, 2021). "The resected Daudi tumor tissue displayed intense CD38 signals." (PMID 34026426, 2021). "In contrast, CD38 blockade decreased the presence of Tregs in the LLC1 tumor microenvironment." (PMID 34771674, 2021). "Furthermore, tumor growth inhibition was associated with decreased intratumoral infiltration of myeloid cells expressing CD11b, CD206, or CD38." (PMID 34835178, 2021). "Importantly, we recently showed that blocking the PD-1/PD-L1 signaling pathway markedly improved anti-CD38 antibody-mediated anti-tumor activity in an anti-CD38 antibody naïve MM mouse model." (PMID 34070044, 2021). "Analysis differences of pathways between A549 CD38 WT and CD38 KO tumor cells by Gene Ontology (GO) and Kyoto Encyclopedia of Genes and Genomes (KEGG), we identified cell cycle, cell proliferation, stress-activated MAPK signaling, cell metabolic, and other signaling pathways were changed." (PMID 34226519, 2021). "Dara has a broad-spectrum killing ability against CD38-expressing tumor cells through multiple mechanisms including complement-dependent cytotoxicity, antibody-dependent cellular cytotoxicity, antibody-dependent cellular phagocytosis, and the induction of cell death through Fc-mediated crosslinking." (PMID 34987512, 2021). "In addition, CD38 in the tumor was positively correlated with infiltrated immune cell signatures in HNSCC." (PMID 34211854, 2021). "In this environment, the use of anti-CD38 mAbs depletes CD38+ MDSCs, T regs, and B regs immune suppressive cells and enhances antitumor activity, but as anti-CD38 mAbs downregulates CD38 expression in tumor cells, immune escape, and disease progression is favored." (PMID 33727923, 2021). "Indeed, MDSC with higher CD38 expression displayed a greater capacity to suppress activated T cells and to promote tumor growth than MDSC with lower CD38 expression." (PMID 33390169, 2021). "Tregs were reduced in the tumor when LLC1-bearing mice were treated with anti-CD38." (PMID 34771674, 2021). "Importantly, PBMCs from daratumumab-treated patients still induced lysis by ADCC of CD38+ tumor cells in vitro." (PMID 32457357, 2021). "Radioimmunotherapy plays a good role in the treatment of CD38‐positive tumor models." (PMID 34026426, 2021). "Furthermore, we established NPG mouse xenograft tumor models to determine the antitumor ability of CD38 CAR-T cells in vivo." (PMID 34513682, 2021). "Recently, preliminary results from a phase II clinical trial (NCT01084252) have demonstrated superior anti-tumor activity of the combination of dexamethasone and isatuximab compared to this anti-CD38 mAb alone in MM patients with at least three prior lines of therapy." (PMID 33799565, 2021). "The relapsing tumor assumed a unique immunophenotype from CD138+/CD38+/CD56- to CD138-/CD38+/CD56-." (PMID 32337142, 2020).
tumor (continued). "Anti-CD38 daratumumab is an example of another mAb that eliminates tumor cells based on multiple mechanisms of action, including complement, which may synergize with each other for maximal antibody efficacy in vivo." (PMID 33126570, 2020). "Indeed, an acidic tumor microenvironment (pH ~ 5.5) significantly favors the CD38/CD203a/CD73 pathway, which leads to the production of adenosine (ADO)." (PMID 33322499, 2020). "Macrophages, neutrophils, eosinophils, and γδ T-cells are able to induce ADCC against tumor cells coated with a therapeutic antibody but whether they play a role in CD38 antibody-induced ADCC is yet unknown." (PMID 32138182, 2020). "Therefore, the anti-CD38 antibody is considered to achieve a better outcome in low tumor burden cases, similarly to blinatumomab in B-ALL." (PMID 33292550, 2020). "Nanobody-based chimeric antigen receptors (Nb-CARs) may provide a basis for the clinical development of novel therapeutics to target CD38-expressing tumor cells." (PMID 32013131, 2020). "Therefore, enhancing CD38 expression level on target tumor cells with ATRA treatment seems to contribute to improved isatuximab-induced ADCC of MM cells." (PMID 32922390, 2020). "For this purpose, we used syngeneic tumor models in immunocompetent mice, and we were able to validate several clinical observations in these mice, including the daratumumab-mediated elimination of CD38+ Tregs and CD38+ MDSCs." (PMID 33321969, 2020). "Importantly, this study suggested that patients who developed antigen (CD38 and tumor)-specific CD4+ and CD8+ T-cell responses, were those who responded to ISA therapy." (PMID 33096610, 2020). "We then sought to test whether isatuximab-activated NK cells were able to efficiently lyse CD38− tumor cells." (PMID 32922390, 2020). "Similarly, experiments with the isotype control heavy chain antibody l-15-hcAb resulted only in background levels of tumor cell lysis, reflecting the inability of this antibody to bind to CD38." (PMID 32194826, 2020). "Indeed, it has been shown that the anti-CD38 mAb Daratumumab enhances effectors cell-mediated lysis, degranulation, and ADCC against CD38+ tumor cells improving the overall response rate in MM patients." (PMID 32610578, 2020). "Here, we investigated whether CD38-specific antibodies also inhibit the enzyme activity of CD38-expressing tumor cells, thereby providing a potential second mode of action." (PMID 33396591, 2020). "Interestingly, we found that the frequency of CD101+CD38+ tumor specific CD8 T cells was significantly lower in cells isolated from the tumors of FOLFOX-treated mice." (PMID 32391270, 2020). "Interestingly, CD38 CAR-T cells were modulated to have a low affinity to discriminate between CD38 high tumor cells and CD38 low normal cells through the redesign of CAR using light-chain exchange technology." (PMID 33121189, 2020). "Next, we evaluated the combined effect of targeting PD-1 and CD38 in J558 tumor-bearing mice." (PMID 33321969, 2020). "To unravel possible combinatorial treatments we determined whether CD38 expression correlates with the tumor inflammation signature (TIS)." (PMID 31960110, 2020). "Indeed, combined targeting of CD38 and PD-1 demonstrated enhanced antitumor activity in a MM mouse tumor model." (PMID 33321969, 2020). "Finally, the most efficacious treatment was with the CD38-targeted nanoparticles, suppressing tumor growth the most among all groups tested." (PMID 33138841, 2020). "Further studies should address the question whether the reducing conditions and other physicochemical features of the tumor microenvironment (pH, hypoxia) similarly effect the enzyme activities of CD38." (PMID 33396591, 2020). "Furthermore, it addresses current and future therapeutic perspectives, with a particular emphasis on the significance of CD38 interaction with immune cells of the tumor microenvironment." (PMID 32225002, 2020).
tumor (continued). "Preclinical studies have highlighted isatuximab's ability to induce Fc-dependent mechanisms such as ADCC, ADCP, and CDC; Fc-independent mechanisms, including the induction of direct cytotoxicity in tumor cells; and inhibition of CD38 enzymatic activities, as well as wider immunomodulatory effects." (PMID 32922390, 2020). "Importantly, CD38 antibodies inhibit CD38 ectoenzymatic activity and rapidly reduce CD38 expression on tumor cells as well as non-tumor immune cells." (PMID 33321969, 2020). "Therefore, under the action of CD38, the tumor microenvironment will eventually reduce extracellular NAD+, change the cascade of calcium signals, and produce immunosuppressive adenosine." (PMID 32875727, 2020). "NK-92 cells expressing CD38-specific Nb-CARs specifically lysed CD38-expressing but not CD38-deficient tumor cell lines." (PMID 32013131, 2020). "In this context, CD38 expression has been regarded as a potential marker of tumor proliferation; its expression fluctuates during the course of the disease and may be acquired or lost by CLL cells according to their proliferation status." (PMID 32225002, 2020). "Our results indicate that Nb-CARs, indeed, may provide a basis for clinical development of novel therapeutics to target CD38-expressing tumor cells." (PMID 32013131, 2020). "To analyze the effects of daratumumab and of nanobody-based hcAbs on the GDPR cyclase activity of living CD38-expressing tumor cells, we incubated CD38-transfected HEK cells or LP-1 cells with CD38-specific hcAbs, daratumumab, or araF-NAD, before addition of NGD+." (PMID 33396591, 2020). "Consistent with this hypothesis, CD38 was overexpressed in 41% (11 out of 27 human lung tumor samples) of tumor cells." (PMID 32092898, 2020). "To elucidate if the non-canonical adenosinergic pathway might have an impact on a radiation-induced tumor response and immunomodulation, we analyzed the expression of CD38 and CD203a/PC-1 in LLC1 tumors grown on WT, CD39−/−, and CD73−/− mice." (PMID 33194619, 2020). "In a NSCLC mouse model, CD38 was found to be upregulated on tumor cells upon resistance to anti-PD-1 axis therapy, which could be reversed with the inhibition of either A2a or CD38." (PMID 33419311, 2020). "We identified the programmed cell death-1/programmed cell death-ligand 1 (PD-1/PD-L1) pathway and MM cell-secreted transforming growth factor-beta (TGF-β) as tumor cell-related features that could suppress CD38-mediated ADCC." (PMID 32922390, 2020). "In order to test whether Nb-CAR-NK cells specifically lyse CD38-expressing tumor cells, we co-incubated Nb-CAR-NK cells with luciferase-transduced CA-46 cells for 4 h at 37 °C before addition of luciferin." (PMID 32013131, 2020). "If the CD138 receptor actively triggers endocytosis, then the CD138 nanoparticles could trigger rapid cellular uptake at a higher rate than CD38, leading to less selectivity for the tumor cells and more off-target losses." (PMID 33138841, 2020). "In addition to isatuximab-mediated NK cell activation via engaging high-level CD38-expressing tumor cells, isatuximab treatment of purified NK cells also led to direct NK cell activation and release of IFN-γ and TNF-α in the absence of target cells." (PMID 32922390, 2020). "Interestingly, the expression level of CD38 on tumor cells also affected NK cell activation in isatuximab-mediated ADCC." (PMID 32922390, 2020). "The wide expression of CD38 among hematopoietic cells might be a critical inconvenient for its clinical application due to possible on-target, off-tumor toxicities." (PMID 32582204, 2020). "Infectious complications may derive from anti-CD38 immunotherapy also targeting CD38-positive immune subpopulations different from tumor plasma cells." (PMID 31963337, 2020). "Moreover, with a longer treatment duration, PD-1 blockade markedly improved anti-CD38 antibody-mediated cytotoxicity in vivo in murine CD38+ tumor models." (PMID 33321969, 2020).
tumor (continued). "Then, tumor-tropic BM-MSCs circulated to primary sites and triggered CD151+/CD38+ cells acquiring EMT-associated CSC properties through IL6R/pY705-STAT3 signaling to promote tumor initiation and were also attracted by and migrated towards the premetastatic niche." (PMID 33262462, 2020). "The metabolic dysfunctionality observed in the CD38 expressing tumor-infiltrating CD4 T cells could also be mediated by the loss of anti-oxidant potential of T cells." (PMID 32709019, 2020). "Furthermore, the relationship between CD38 expression level and immune cell infiltration was analyzed by the Tumor Immune Estimation Resource and TISIDB." (PMID 32425977, 2020). "However, CD38 expression was significantly lower on tumor cells from pPCL patients compared to NDMM patients (p = 0.037)." (PMID 33321969, 2020). "Therefore, HDAC inhibitors can be expected to promote anti-tumor immunity in the context of immune cell activation with the therapeutic anti-CD38 antibody daratumumab." (PMID 30956773, 2019). "The elevated TNFR2+CD38+HLA-DR+CD8+ TILs indicated that TNFR2 might be involved in the anti-tumor response." (PMID 31649684, 2019). "This suggested the existence of functionally-distinct macrophage subsets, with CD38 marking a subpopulation of pro-inflammatory macrophages that may play a role in tumor suppression." (PMID 31552039, 2019). "Co-targeting of CD38 and PD-L1 improves anti-tumor immune response." (PMID 31402913, 2019). "Furthermore, treatment of patients with anti-CD38 antibodies is followed in vivo by a strong release of EVs at the tumor site, where they interact with infiltrating cell populations." (PMID 31783629, 2019). "In addition, CD38 antibodies potentiate the host anti-tumor immunity through physical elimination of Tregs and Bregs, as well as MDSCs that typically exert immune-suppressive functions." (PMID 31783629, 2019). "Data generated from our laboratory suggested that the enzymatic function of CD38 on the tumor cells is integral to the immunosuppressive microenvironment, namely through the accumulation of adenosine and adenosine receptor activation on tumor infiltrating T cells." (PMID 31878283, 2019). "Several AML tumour-associated antigens are at the forefront of targeted therapy development, which include CD33, CD123, CD13, CLL-1 and CD38 and which may be present on both AML blasts and leukemic stem cells." (PMID 31434267, 2019). "Both, CD38highMDSC cells-mediated suppression of activated T-cells and the concomitant expression of CD38 with exhaustion markers on T cells, for example PD1, pointed to an active role of CD38 in modulating T cell metabolism and fate toward the generation of an immune tolerant landscape in tumor." (PMID 31402913, 2019). "Altogether, our results suggest that CD38+ macrophages are associated with an M1 phenotype that is characterized by higher CD80 expression and a pro-inflammatory cytokine profile, all of which contribute to the anti-tumor immune response." (PMID 31552039, 2019). "One possible approach to ameliorate resistance to PD-1/PD-L1blockade is co-inhibition of CD38, which may re-establish the immune response of T cells to the tumor." (PMID 31214171, 2019). "CDC function was an important feature of Daratumumab, while less of other anti-CD38 antibodies could kill tumor cells by CDC function." (PMID 31118070, 2019). "The current status of the field points to CD38 as capable of shifting the local tumor metabolic microenvironment from pro-inflammatory to anti-inflammatory, indicating CD38 as a potential mechanism of resistance to currently approved immunotherapy agents, such as PD(L)-1 blocking antibodies." (PMID 31878283, 2019). "This may indicate the presence of various macrophage subsets with different functions, where the CD38+ macrophage subset may serve to promote inflammation and exert anti-tumor effects." (PMID 31861847, 2019).
tumor (continued). "CD38, a transmembrane glycoprotein that lacks an internal signaling domain, is a surface molecule expressed by normal T, B, NK and myeloid populations as well as by different tumor cells." (PMID 31068926, 2019). "Another tumor-suppressive mechanism mediated by CD38 inhibition may be a reduction in TME adenosine levels." (PMID 31861847, 2019). "Collectively, these studies pinpointed that CD38 is crucial for in vivo Treg modulatory functions and generation, and confirmed CD38 targeting approach by mAbs as efficient treatment to deplete CD38hi Tregs and revert tumor-induced immune-modulation." (PMID 31783629, 2019). "The high degree of variability in the number and activity of these CD38+ TILs between patients could explain the inter-individual variance in anti-tumor responses following immunotherapy." (PMID 31861847, 2019). "Tumor escape from PD-1/PD-L1 blockade is thought to be mediated by CD38 expression on T cells." (PMID 31462637, 2019). "CD38 has long been considered an immune molecule due to its ubiquitous expression across the immune system, and previous studies have shown that CD38 serves a complex, multifactorial role in the promotion of tumor growth and resistance to cancer immunotherapy." (PMID 31861847, 2019). "Tumor cell death was significantly higher in CD38 KO mice, and follow-up studies demonstrated that similar results can be obtained with pharmacological targeting of CD38 through the administration of the inhibitor K-rhein, which is a flavonoid frequently used as pharmacologic inhibitor of CD38." (PMID 31878283, 2019). "Indeed, CD38 is located on the mPC surface as well as adjacent non-tumor cells catalyzing the conversion of NAD+ to cyclic adenosine diphosphate ribose (cADPR) via cyclase activity and cADPR to ADPR via hydrolase activity." (PMID 31068926, 2019). "This transfer occurs via a CD38-dependnet tumor-derived tunneling nanotubes." (PMID 31214171, 2019). "Thus, the present review will provide an overview of CD38 enzymology; focus on recent advances in CD38-mediated age-related metabolic dysfunction and tumor immunometabolism; and summarize pharmacological approaches to CD38 inhibition." (PMID 31214171, 2019). "However, the efficacy of these methods is hindered by high rates of resistance that develop following treatment, potentially due to the upregulation of CD38 expression on NSCLC tumor cells." (PMID 31861847, 2019). "Furthermore, FcγR-mediated cross-linking of daratumumab induces programmed cell death of CD38-positive MM tumor cell lines." (PMID 31779273, 2019). "However, establishing clear contribution of adenosine pathway signaling to the anti-tumor activity of anti-CD38 antibodies has been confounded by technical challenges of directly measuring adenosine levels in patients." (PMID 31779273, 2019). "Results have also revealed the tumor-specific activation of TNFR2 in CD38+HLA-DR+CD8+ TILs." (PMID 31649684, 2019). "Loss of CD38 did not affect the amount of mitotic cells, but increased caspase-3 activation, suggesting that the reduction in tumor volume was mediated by increasing cell death and not by inhibiting cell proliferation." (PMID 30159123, 2018). "On the other hand, the anti-tumor activity of CD38-specific CAR T cells may be enhanced through the combination of these cells with conventional therapies, such as checkpoint inhibitors." (PMID 30546360, 2018). "We further assessed the effect of CD38 on tumor vascularization." (PMID 30159123, 2018). "Hence inhibition of CD73, A2AR or CD38 in combination with anti-PD-1, has been shown to elicit enhanced anti-tumour T cell responses mediated by enhanced IFNγ and Granzyme B expression by CD8+ T cells." (PMID 30513816, 2018). "In addition a recent study showed the CD38-NAD+ axis regulates anti-tumor T cell response in immunotherapy." (PMID 30159123, 2018).